IL6 (interleukin 6)
Diseases named in the same sentence as IL6 in open-access papers (continued):
Sharing a sentence is not in itself a finding about the gene and the disease.
tumor (continued). "The synchronous evaluation of 12 cytokines showed that preoperative plasma levels of the proinflammatory cytokines IL-6, IL-8, IL-1β, TNFα were significantly lower in healthy donors versus CRC patients and that such differences progressively increase with tumor stage." (PMID 24040252, 2013). "In their case, although tumor cells secrete IL-6, IL-6 did not affect the proliferation of tumor cells." (PMID 23710188, 2013). "Furthermore, P276-00 inhibited expression of soluble proteins such as IL-6, EGFR and HSPA8 that promote tumor microenvironment." (PMID 23414419, 2013). "In cancer cell lines and in patient tumor tissues, there is evidence for constitutive activation of STAT3 through chronic cytokine stimulation through autocrine and/or paracrine loops, often involving IL-6." (PMID 24324713, 2013). "Moreover, the pro-inflammatory mediators IL6 and IL8 were significantly overexpressed in the tumours, while IL12A was significantly downregulated." (PMID 23570247, 2013). "Results showed that administration of anti-IL-6 mAb but not rat IgG antibody significantly inhibited tumor growth and p-Stat3 expression in wild-type mice." (PMID 24453427, 2013). "By activating TLRs, these miRNAs trigger the NF-kappaB pathway which ultimately leads to an increased production of interleukin-6 (IL-6) and tumor necrosis factor-alpha (TNF-alpha) by the immune cells, leading to increased tumor growth and metastatic potential." (PMID 23802096, 2013). "The IHC data for TMA slides demonstrated that IL-6 was overexpressed in tumor tissues compared to adjacent non-malignant epithelial tissues." (PMID 23561329, 2013). "Immunofluorescence microscopy of different tissues from 4T1 cell-bearing mice indeed showed that MDSCs in the primary tumor mass and metastatic lung, but not in the spleen, expressed high levels of IL-6." (PMID 24021059, 2013). "According to current study, we suggest that the enhancement of angiogenesis might partly attribute to the increased expression of angiogenic factors including TGF-β, VEGF, IL-6 and MIP-2 by hBM-MSCs when interacting with tumor cells." (PMID 23763837, 2013). "On serial section, CYGB, PI3K, p-Akt, IL-6, TNFα and VEGF could be detected in the same area of tumor cells, at least in a part of them." (PMID 23688241, 2013). "Since activation of IL-6/STAT3 axis signaling in cancer stem cells (CSC) enhances proliferation and survival as well as tumor growth in mice, we decided to detect the presence of CSC in HepG2 cells uninfected and infected with HCMV using a tumorsphere formation assay." (PMID 23555719, 2013). "The biological mechanisms linking tumor aggressiveness in IL-6, IL-8 and TNF- α are not clearly understood." (PMID 23637926, 2013). "Asra-EPS cell line had epithelial and mesenchymal features similar to those of the original tumor as revealed by immunohistochemistry, secreted CA 125, IL-6 and VEGF, did not express INI-1, and exhibited tumorigenicity in nude mice." (PMID 23915498, 2013). "The immune cells from pulchellin-treated mice also produced statistically higher concentrations of TNF-α by PEC cells, and IL-4, IFN-γ and IL-10 by splenocytes, and lower concentrations of IL-6 (PEC cells) and TGF-β (splenocytes), than the cells from tumor control mice." (PMID 22827934, 2012). "Since tumor-infiltrating MDSCs have the highest immunosuppressive potential among different MDSC sub-populations, we simulated the maturation of BM precursors to MDSCs using a combination of GM-CSF and IL-6, in vitro." (PMID 22762146, 2012). "Tumour stromal cells, including macrophages, dendritic cells and fibroblasts, release several inflammatory cytokines, such as TNF-α, IL-1 and IL-6, which attract and recruit more inflammatory cells to the tumour microenvironment to further enhance the proliferation and survival of tumour cells." (PMID 23905066, 2012).
tumor (continued). "Both tumor-bearing groups (SE and EE housing) had increased resistin, IL-6, TNF-α, PAI-1 and MCP-1 levels irrespective of the different housing environment demonstrating higher inflammatory response due to the presence of the tumor." (PMID 23272114, 2012). "We have indication that IL-6 and CCL-2 levels are increased in our OTC tumor model." (PMID 22792213, 2012). "In the early stages, accumulation of Th17 cells in tumor tissues may be supported by high concentrations of TGF-β and IL-6." (PMID 22994684, 2012). "In addition to GM-CSF, IL-1β, IL-6, and IL-17, inflammatory cytokines frequently induced after therapies can also drive MDSC expansion in tumor." (PMID 22778760, 2012). "Non-tumor-bearing EE mice showed a significant increase in adiponectin levels but no change in those of leptin, F2-isoprostanes, PGF2α, IL-6, TNF-α, PAI-1, and MCP-1 levels." (PMID 23272114, 2012). "A higher IL-6 and IL-8 production was also detected after infection with H. pylori pretreated with patient 4 soluble tumor mucins already at 10 μg/mL (data not shown) and with three antral mucin samples at 50 μg/mL." (PMID 22563496, 2012). "The study aimed to evaluate, during colorectal carcinogenesis from benign to malignant phases: i) the trend of serum levels of IL-8, IL-6, TGFβ1, VEGF and MMPs; ii) the parallel trend of CRP serum levels; iii) derangement of the principal TGFβ1 receptors (TGFβ1RI/RII) in tumor tissues." (PMID 22848630, 2012). "Some of the study populations are relatively small and rely on evaluation of IL6 levels in the serum or saliva rather than in tumor tissues." (PMID 23185547, 2012). "This crosstalk is initiated by the release of IL-6, resulting from the NFκB-dependent activation of the IL-6 promoter, and the subsequent tyrosine phosphorylation of STAT3 by the autocrine/paracrine activation of IL-6 receptors in tumor cells." (PMID 22545054, 2012). "The treatment of PCa cells with CDF, a novel Curcumin-derived synthetic analogue previously showed anti-tumor activity in vivo, inhibited the productions of VEGF and IL-6, and down-regulated the expression of Nanog, Oct4, EZH2 mRNAs, as well as miR-21 under hypoxic condition." (PMID 22952749, 2012). "Other studies have been initiated to investigate the clinical significance of IL6 expression in tumor cells, rather than measuring serum or saliva IL6 levels, but the results are still controversial." (PMID 23185547, 2012). "As described by many groups, IL-6 is produced by both lymphoid and nonlymphoid cells, such as T cells, B cells, monocytes, endothelial cells, fibroblasts and many tumor cell types." (PMID 22236378, 2012). "IL-8 and other cytokines such as IL-6 have been shown to play a critical role in tumor growth in multiple cancer models independent of inflammation such as in Ras-driven models of cancer." (PMID 22988345, 2012). "One experimental study has shown that human lung CSC-derived tumor contained 2–3 higher levels of inflammatory cytokines including IL-6, which is consistent with recent findings showing that the lung CSC-like cells have high level expression of IL-6/IL-6R." (PMID 22952749, 2012). "Collectively, these data suggest that unlike high PGE2 secretion, high basal IL-6 secretion or PGE2 mediated induction of IL-6 secretion, are not necessarily hallmarks of tumor promoting fibroblasts." (PMID 21957456, 2011). "In this study, the TG2 and downstream IL-6 signaling pathway may act as a convergence site for EMT and cancer-initiating cell phenotypes, leading to enhanced local tumor growth and distant hematogenous metastasis." (PMID 21967801, 2011). "Indeed, hypoxic cancer cells secrete various cytokines, such as IL-6, VEGF, PDGF and FGF, that attract and promote MSC proliferation and differentiation into tumor-supporting cells." (PMID 21738685, 2011). "Levels of the pro-inflammatory cytokines IL-6 and IL-8 are elevated in EOC ascites suggesting that they could play a role in tumor progression." (PMID 21619709, 2011).
tumor (continued). "The level of IL-6 was changed during tumor growth without any correlations to activation waves observed in peritoneal macrophages." (PMID 21760797, 2011). "Cell proliferation was comparable between HCC cells only and tumor cells treated with or without IL-6 antibody or STAT3 inhibitor." (PMID 22136659, 2011). "In relation to their ‘tunable’ function, mast cells in the local environment can also be detrimental for the tumours themselves, secreting immune mediators such as IL-1, IL-4, IL-5, IL-6 and TNF-α that can induce apoptosis of tumor cells and recruit inflammatory cells." (PMID 24212964, 2011). "Ligands for CD194 (e.g., CCL17 or CCL22) were in contrast to IL-6 and TGF-β not highly expressed in the tumor tissue, altogether indicating a conversion from CD8+ rather than a tumor-directed migration as the cause for the observed infiltration." (PMID 22110523, 2011). "IL-6 production from cancer cells was dependent on TG2 expression, and tumor-sphere formation was correlated with TG2-dependent IL-6 production in cancer cells, indicating that the effect of TG2 on tumor-sphere formation is mediated through downstream IL-6 production." (PMID 21967801, 2011). "Oppositely to TNF-α and VEGF, serum level of IL-6 was changed in tumor-bearing mice but it did not correlate with alterations in macrophage activity or other effects." (PMID 21760797, 2011). "As would be expected, TAMs possess M2-like traits; Tumour cells and the tumour microenvironment release a variety of factors that facilitate this, including IL-4, IL-6, IL-10, PGE2, TGF-β1 and CSF-1, expressed by tumour cells, as well as IL-10, PGE2 and MMP-7 expressed by TAMs." (PMID 22005011, 2011). "In conclusion, our results suggested that the IL-17 mediated tumor-promoting role involved a direct effect on tumor cells through IL-6 induction by activating the AKT pathway; IL-6 in turn activated JAK2/STAT3 and up-regulated proinvasive factors IL-8, MMP2, and VEGF both in vitro and in vivo." (PMID 22171994, 2011). "It was inferred from microarray analyses of tumour cell-MSC co-cultures that several cytokines may be expressed in the tumour cells that act to promote these effects: CXCL1, CXCL5 and CXCL6, IL-6 and IL-8." (PMID 21902837, 2011). "Indeed, we found that CD277 is up-regulated in monocyte-derived DCs by multiple inflammatory cytokines and hypoxia-induced mediators commonly found in the tumor microenvironment, including VEGF, and CCL3 and, to a lesser extent, IL-6." (PMID 21113407, 2010). "IL-6 was added to tumour cells in 3D cultures but we failed to observe any stimulation of tumour cell invasion." (PMID 20723242, 2010). "Previous studies have reported that when tumor cells are stimulated with lipopolysaccharides (LPS), the ligand for TLR4, the proinflammatory factors such as nitric oxide, IL-6 and IL-12 are expected to be released from tumor cells, attracting and activating inflammatory cells." (PMID 20618976, 2010). "Secondly, residual hepatic VX2 carcinoma might facilitate rapid tumor progression through induction of overexpression of multiple molecular factors, such as PCNA, MMP-9, VEGF, HGF and IL-6." (PMID 20667141, 2010). "Invasion of tumour cells by addition of a single cytokine (IL-6) was not enough to trigger the complex process of tumour cell invasion." (PMID 20723242, 2010). "During tumor initiation, TAMs create a favorable environment for tumor growth by secreting epidermal growth factor (EGF), platelet-derived growth factor (PDGF), TGF-β, IL-6, IL-1, and tumor necrosis factor (TNF)-α." (PMID 21437225, 2010). "To determine the consequence of the IL-6 and TGF-β increment, we investigated the cytokine-coupled transcriptional factor signals of STAT3 and Smad3 which were identified as important factors responsible for malign tumor progress." (PMID 20520770, 2010). "Here we also demonstrate a requirement for IL-6 in MCF10A-Ras mediated tumor formation with no apparent effect on 2-D growth." (PMID 20929542, 2010).
tumor (continued). "This indicates that IL-6 is essential but not sufficient alone to stimulate fibroblast induced invasion of tumour cells." (PMID 20723242, 2010). "When marrow is invaded by BC cells, osteoclasts are recruited and differentiated at an increased rate by the production of high amounts of tumor-derived cytokines such as transforming growth factor β (TGF-β), interleukin-6 (IL-6), parathyroid hormone-related protein (PTHrP)." (PMID 20416078, 2010). "The results showed that hBD-3 induced the expression of IL-1α, IL-6, IL-8, and CCL18, suggesting that hBD-3 may activate macrophages and stimulate their tumor-promoting capacity." (PMID 20544025, 2010). "The majority of these studies have shown that IL-6 levels were higher in malignancies than in non-malignancies, and increased with increasing tumor size and depth." (PMID 19457231, 2009). "Growth factors stain in patches that do not correlate with the more sparse staining patterns of the TAF markers themselves due to the fact that the tumor cells also secrete the growth factors HGF, IL-6 and EGF in the presence of MSC as demonstrated by in vitro co-culture data." (PMID 19352430, 2009). "Our previous and current data suggest that targeting Stat1, IL6 and IL8 may enhance the therapeutic ratio for treatment of Stat1 over-expressing tumours." (PMID 19437244, 2009). "Conversely, IL-6 has recently been shown in an epithelial tumor cell line to activate NFκB signaling through non-canonical binding of unphosphorylated STAT3 (U-STAT3) to NFκB, releasing inhibition by IκB." (PMID 19436757, 2009). "The in vitro presence of MSC, MSC-conditioned medium EGF and IL-6 is essential to the growth of tumor cells in a controlled Matrigel environment without the presence of MSC." (PMID 19352430, 2009). "IL-6 and IL-10 may help identify a subset of HCC patients may serve as complementary tumor markers in these patients." (PMID 27942274, 2009). "In intact mice without castration, the growth of LNCaP/IL-6#1 tumour was significantly faster than that of LNCaP/Co tumour." (PMID 19844233, 2009). "Preoperative serum IL-6 and CRP levels were related to cancer stage and might be markers of tumor invasion, LN metastasis and TNM stage." (PMID 19457231, 2009). "Preoperative serum IL-6 and CRP levels might be markers of tumor invasion, LN metastasis, and TNM stage." (PMID 19457231, 2009). "Proliferation assays were then carried out to evaluate whether the increased availability of IL-6 and CCL5 in a neoplastic microenvironment would affect the growth of the LNCaP tumour cell line." (PMID 19242540, 2009). "The lack of this difference might result from the production of cytokines and growth factors (like interleukin-6 and VEGF) by tumor cells." (PMID 19519895, 2009). "The tumor promoters 12-phorbol-13-myristate-acetate (PMA) and staurosporine or the anti-estrogen tamoxifen, H2O2 producing oxidative stress, leptin, IL-6 or staphylococcal endotoxin B, activin or anisomycin, did not significantly influence CCHCR1 mRNA levels (data not shown)." (PMID 19551138, 2009). "In addition, we demonstrate that both IL-6 and CCL5 promote the proliferation of LNCaP tumour cells reaching their maximal activity synergistically." (PMID 19242540, 2009). "The clear correlation between the pre-RT plasma levels of IL-6 and TGF-β1 and the respective cytokine production in the corresponding tumour biopsies suggests that the elevated plasma levels in NSCLC patients result from the over-production in their tumours." (PMID 18682839, 2008). "Interestingly, IL-6 is activated in ICU patients and has been reported to increase mir-21 in tumour cell lines mediated via STAT3." (PMID 18997871, 2008). "In contrast, the clear correlations of IL-6 and TGF-β1 plasma levels with the cytokine production in corresponding tumour biopsies and with the individual tumour responses suggest that the tumour is the major source of circulating cytokines in patients receiving RT for advanced NSCLC." (PMID 18682839, 2008).
tumor (continued). "Furthermore, it has been reported that IL-6 was able to induce degradation of Cdc25A by STAT3 activation, which would form a repressor complex with the Rb tumour suppressor to occupy the Cdc25A promoter and block its induction." (PMID 17987036, 2007). "However, IL-1β, IL-6, IL-8, IL-10, IL-12, MCP-1 and MIP-1β were more abundant in high-grade tumours than in low-grade tumours." (PMID 17261184, 2007). "However, several cytokines produced by monocytes (IL-1β, IL-6 and MCP-1) or macrophages (such as IL-1β, IL-6, IL-8, MIP-1β and TNF-α) are highly expressed by the tumour." (PMID 17261184, 2007). "Using interphase FISH approach, no IL-6 gene amplification was detected in low-grade or anaplastic tumours (n=17), whereas high-level amplification was found in 15 out of 36 (41.7%) GBM." (PMID 17224923, 2007). "The complete tumour resection, equally distributed among patients with and without IL-6 gene amplification, was an independent factor of favourable prognosis (RR complete vs partial 0.31; P=0.013)." (PMID 17224923, 2007). "IL-1β, IL-6, IL-8, IL-10, IL-12, MCP-1 and MIP-1β were abundant in high-grade tumours." (PMID 17261184, 2007). "The rapid activation of STAT3 signaling pathways may explain the ability of IL-6 to rescue cells from TGF-β1-mediated growth inhibition, since STAT3 is known to mediate proiliferative and anti-apoptotic signaling in normal and tumor cells." (PMID 17324269, 2007). "However, cytokine protein concentrations were significantly elevated in the tumour tissue: IL-1β 136 pg mg−1 of total protein (IQR 41–425), P=0.007; IL-6 3 pg mg−1 (IQR 0–46), P<0.05; IL-8 56 pg mg−1 (IQR 23–159), P=0.007; TNF-α 7 pg mg−1 (IQR 1–26), P<0.05." (PMID 17088911, 2006). "We hypothesise that in this subgroup of MM patients with clinically relevant osteolytic lesions, a high tumour load can be assumed anyway, while the malignant potential is better indicated by CRP as surrogate marker for IL-6 levels." (PMID 16969356, 2006). "In our study, gene transcription of TNFα and IL-6 in white fat was not affected with tumour burden, in agreement with our previous report that their circulating levels were unchanged in cachectic mice." (PMID 17047651, 2006). "The prognostic value of IL-6 has been described in many tumor types, but not yet in HNSCC treated by radiotherapy ± chemotherapy." (PMID 15847702, 2005). "Baseline plasma IL-6 concentrations did not correlate with tumour behaviour before or after rhIL-6 treatment." (PMID 8611381, 1996). "The generated CD4+ T cells secreted interferon (IFN)-gamma, tumour necrosis factor (TNF)-alpha, TNF-beta, and interleukin (IL)-6 (but not IL-4), and exhibited a high level of cytolytic activity against several tumour cell lines." (PMID 8554971, 1996). "Moreover, injection of migrasomes derived from Renca cells expressing ITM2B1‐115 but not ITM2BI115A effectively activated IL‐6 signaling in tumor tissues from corresponding allografts." (PMID 41319268, 2026). "However, when CAR-T cells were co-cultured with antigen-presenting cells (macrophages or iDCs) and tumor cells, the core CRS cytokine IL-6 was significantly elevated in an in vitro cell culture model, indicating that this system effectively mimics cytokine release during CAR-T-induced CRS." (PMID 41669611, 2026). "Notably, immune‐related pathway activities, including TNFα signaling, interferon pathways, and IL6‐JAK‐STAT3 signaling, were reduced in stiff tumors, suggesting a diminished immune response potentially from altered structural characteristics of the tumor." (PMID 40988561, 2026). "Additionally, SASP components like IL-6 and IL-8 activate STAT3 signaling, promoting epithelial–mesenchymal transition (EMT)-related gene expression and MMP production, which facilitate cancer cell growth, invasion, metastasis, and tumor vascularization." (PMID 40563615, 2025).